PTX3 (pentraxin 3)
Diseases named in the same sentence as PTX3 in open-access papers (continued):
Sharing a sentence is not in itself a finding about the gene and the disease.
COVID-19 (continued). "However, the specific impact of PTX3 on COVID-19 progression is still unclear due to the lack of large multicenter trials as well as the few studies in the literature because of the short time from the pandemic." (PMID 36834949, 2023). "We identified higher levels of D-dimer, IL-6, IL-8, IL-13, Angpt-2, Pentraxin-3, S100B, MMP-8, and u-PAR in the plasma of critical COVID-19 non-survivors than in that of survivors." (PMID 39507250, 2024). "On admission, there were higher serum concentrations of tumor necrosis factor α (TNFα) (p < 0.001), interleukin 1 β (IL-1β) (p < 0.001), pentraxin 3 (PTX3) (p < 0.001), resistin (p = 0.032), and lower concentrations of adiponectin (p < 0.001) between the severe COVID-19 and the non-severe patients." (PMID 36289725, 2022).
glioma (44 papers, 2014 to 2025). A benign or malignant brain and spinal cord tumor that arises from glial cells (astrocytes, oligodendrocytes, ependymal cells). "Subsequent studies should prioritize the validation of these findings in larger cohorts and the exploration of the underlying mechanisms through which PTX3 influences glioma progression and patient outcomes." (PMID 40656950, 2025). "In conclusion, our survival analysis not only elucidates the prognostic implications of PTX3 and its associated gene network but also paves the way for further investigation into their roles within glioma biology." (PMID 40656950, 2025). "Our findings demonstrate a significant association between PTX3 expression levels and survival outcomes in glioma patients, highlighting its prognostic value across various clinical phenotypes." (PMID 40656950, 2025). "The findings demonstrate that elevated PTX3 expression in glioma is associated with disease progression, poor prognostic outcomes, and abnormal immune cell infiltration." (PMID 40656950, 2025). "In summary, the immune cell infiltration patterns associated with PTX3 expression highlight its potential as a key regulator of the glioma immune microenvironment." (PMID 40656950, 2025). "In glioma cells, PTX3 knockdown was associated with a significant reduction in cell proliferation, migration, and invasion." (PMID 39594709, 2024). "We show that IDH1 mutational status determines expression of innate-immune molecule long pentraxin 3 (PTX3), which negatively regulates autophagic flux and genes associated with ferritinophagy in gliomas." (PMID 37476290, 2023). "To identify the PTX3‐associated immune functions in glioma, we performed Gene Ontology (GO) analysis in the TCGA dataset and CGGA dataset." (PMID 35855654, 2022). "Elevated PTX3 expression has been associated with an increased risk of several malignancies, including glioma, liposarcoma, lung carcinoma, and pancreatic carcinoma." (PMID 27458153, 2016). "Elevated expression of PTX3 has also been associated with increased risk of liposarcoma, glioma, lung cancer, prostate carcinoma, and pancreatic carcinoma." (PMID 24457902, 2014). "The association between PTX3 and this pathway suggests that PTX3 may contribute to glioma cell survival and proliferation, highlighting its potential as a therapeutic target." (PMID 40656950, 2025). "In pan‐gliomas, tumors with CN loss had lower expression of PTX3 compared to tumors with CN gain." (PMID 35855654, 2022). "Meanwhile, PTX3 has been associated with the tumor grade and malignancy of gliomas." (PMID 35855654, 2022). "To determine whether the level of PTX3 expression was associated with specific genomic characteristics in gliomas, we performed CNV and somatic mutation analysis in the TCGA dataset." (PMID 35855654, 2022). "Taken together, PTX3 has the potential to become a diagnostic marker for gliomas." (PMID 35855654, 2022). "In this work, we also prove PTX3 expression is associated with aggressive type of glioma." (PMID 32984316, 2020). "Pentraxin 3 (PTX3) was significantly associated with the presence of a high-grade glioma tumor." (PMID 27344170, 2016). "PTX3 has been suggested to play a significant role in tumor-associated inflammation and was shown to be up-regulated in several malignancies, including liposarcoma, lung cancer, pancreatic cancer, and glioma." (PMID 24457902, 2014). "This study aims to address this gap by evaluating the expression levels of PTX3 and its correlation with patient prognosis in glioma." (PMID 40656950, 2025). "PTX3 expression has been reported in numerous malignancies, including glioma, lung, ovarian, pancreatic, and prostate cancers, as well as myxoid liposarcoma and esophageal squamous cell carcinoma." (PMID 41515435, 2025). "To assess the differences in PTX3 protein expression between adjacent paracancerous and glioma tissues, we employed IHC to examine the expression levels of PTX3 in both tissue types." (PMID 40656950, 2025).
glioma (continued). "Our findings further emphasize the critical role of PTX3 in glioma, particularly regarding patient prognosis and immune infiltration." (PMID 40656950, 2025). "Our study aims to address this gap by exploring the potential of PTX3 as both a prognostic biomarker and a therapeutic target in glioma." (PMID 40656950, 2025). "The inhibition of glioma cell growth and migration upon PTX3 knockdown suggests that PTX3 plays a role in promoting glioma progression." (PMID 40656950, 2025). "In summary, this study highlights the critical role of PTX3 in glioma, underscoring its potential as both a prognostic biomarker and a therapeutic target." (PMID 40656950, 2025). "Further investigation is essential to elucidate the mechanisms by which PTX3 influences immune cell dynamics and to explore its feasibility as a therapeutic target in glioma treatment strategies." (PMID 40656950, 2025). "Several clinical studies have demonstrated that PTX3 expression varies among glioma grades and correlates with histopathological classification and disease severity." (PMID 41515435, 2025). "Immunohistochemistry confirmed elevated PTX3 protein expression in both lower-grade glioma and glioblastoma multiforme." (PMID 40656950, 2025). "In order to evaluate the function of PTX3 in glioma, a series of in vitro experiments were conducted." (PMID 40656950, 2025). "This study investigates the role of PTX3 expression in glioma and its correlation with patient outcomes, addressing a gap in current research regarding its molecular mechanisms." (PMID 40656950, 2025). "This study investigates the expression levels of PTX3, a key component of the IL-18 signaling pathway, and its implications for the prognosis of glioma patients." (PMID 40656950, 2025). "PTX3, an important immunomodulatory molecule in glioma, has been reported to enhance macrophage infiltration and migration and to promote the malignant transformation of dendritic cells in the tumour microenvironment." (PMID 39903772, 2025). "Univariate Cox regression analysis identified WHO grade, IDH status, 1p/19q codeletion, age, and PTX3 expression as independent prognostic markers for glioma patients." (PMID 40656950, 2025). "Our immune analysis revealed a significant correlation between PTX3 expression and the infiltration of various immune cells in glioma tissues." (PMID 40656950, 2025). "Pan-cancer analysis indicated that PTX3 is markedly upregulated in various cancers, especially gliomas, highlighting its potential as a biomarker." (PMID 40656950, 2025). "Although previous studies have identified several molecular markers relevant to glioma, the precise functions and mechanisms of PTX3 remain insufficiently understood, highlighting a significant gap in the existing literature." (PMID 40656950, 2025). "We anticipate that identifying PTX3 will enhance personalized treatment strategies for glioma patients and support more informed treatment decisions." (PMID 40656950, 2025). "The upregulation of PTX3 in glioma tissue correlates with poor clinical outcomes, suggesting its role in promoting the invasiveness of this malignancy." (PMID 40656950, 2025). "IHC results showed that PTX3 expression was significantly higher in glioma tissues compared to adjacent paracancerous tissues." (PMID 40656950, 2025). "Significant differences were observed in WHO grade, IDH status, 1p/19q codeletion, age, histological classification, OS, DSS, and PFI between glioma patients with high and low PTX3 expression levels." (PMID 40656950, 2025). "In our study, we observed an upregulation of PTX3 in gliomas, while its downregulation in 20 different cancer types suggests a potential tumor-suppressive role in these contexts." (PMID 40656950, 2025). "The differential expression of PTX3 across glioma subtypes suggests its potential role in regulating tumor behavior and patient outcomes through underlying biological mechanisms." (PMID 40656950, 2025).
glioma (continued). "Since 2011 and 2013, several researchers have investigated PTX3 expression in samples from patients with gliomas." (PMID 38730589, 2024). "In glioma cells, PTX3 is suggested to be regulated by spen paralogue and orthologue C-terminal domain containing 1 (SPOCD1), further highlighting its involvement in metastatic processes." (PMID 39594709, 2024). "Previous studies have also demonstrated differential levels of circulating PTX3 between histological subtypes of gliomas and lung cancer." (PMID 38542446, 2024). "Studies on PTX3 RNA expression have involved the investigation of various malignancies, including gliomas, glioblastomas, HCC, head and neck squamous cell carcinoma, melanoma, papillary thyroid carcinoma, and lung cancer." (PMID 39594709, 2024). "In contrast, a recent study reported that PTX3 is highly expressed in gliomas compared to normal brain tissue." (PMID 39201656, 2024). "A diminished expression of PRMT1 (protein arginine methyltransferase 1) and its target asymmetric dimethyl H4R3 mark in IDH1-MT was concomitant with reduced PTX3 in IDH1-MT glioma cells and in patients." (PMID 37476290, 2023). "Ultimately, the additional examination unveiled the prognostic significance of PTX3 in the glioma group, establishing it as the utmost valuable prognostic indicator in patients with GBM." (PMID 37781198, 2023). "Higher levels of PTX3 were observed in glioblastomas, whereas its expression in low‐grade gliomas and normal astrocytes is very low or null, and higher levels of PTX3 are associated with a high degree of malignancy and shorter patient survival." (PMID 37063077, 2023). "Several tumors express PTX3, including lung cancer, glioma, ovarian cancer, myxoid liposarcoma, prostate carcinoma, esophageal squamous cell carcinoma and pancreatic cancer." (PMID 37025408, 2023). "The analysis of cell proliferation showed that the increased expression of PTX3 enhanced the ability of glioma cells to proliferate." (PMID 37781198, 2023). "According to the CCK8 assay and EDU assay, it was found that the excessive expression of PTX3 enhanced the glioma cells’ capacity for cell proliferation." (PMID 37781198, 2023). "In order to assess the glioma cohort’s cell proliferation and invasion capability of PTX3, we subsequently conducted experiments on glioma cells to measure their cell proliferation ability." (PMID 37781198, 2023). "We also found that PTX3 displayed higher expression in secondary and recurrent gliomas than in primary gliomas." (PMID 35855654, 2022). "The deletions of 4q, 9p, 13q, 19q, and the amplification of 4q12, 8q23‐24, 12p13‐14, and 19q more regularly occurred in gliomas with low expression PTX3." (PMID 35855654, 2022). "In summary, we revealed the characteristics of PTX3 in the tumor development and the tumor immune microenvironment of gliomas." (PMID 35855654, 2022). "Nevertheless, PTX-3 expression in gliomas is positively correlated with monocytes, fibroblasts, endothelial, and T cell levels." (PMID 36499628, 2022). "In summary, we revealed the characteristics of PTX3 in the development of gliomas and the tumor immune microenvironment of cancer." (PMID 35855654, 2022). "Our study was expected to provide the background support for further in‐depth research about PTX3 in gliomas." (PMID 35855654, 2022). "This is the first extensive study of the prognostic value and immune‐related characteristics of PTX3 in gliomas, with particular attention being paid to the potential role of PTX3 in regulating macrophages." (PMID 35855654, 2022). "We further investigated the mRNA expression levels of PTX3 in different grades of gliomas in the CGGA cohort." (PMID 35855654, 2022). "High expression of PTX3 was associated with reduced progression‐free interval (PFI) and disease‐specific survival (DSS) in LGG and pan‐glioma samples in the TCGA dataset." (PMID 35855654, 2022). "It is expected that characterizing the landscape of PTX3 in glioma will help promote the clinical management of glioma." (PMID 35855654, 2022).
glioma (continued). "By its expression pattern in the TCGA cohort in our previous finding, there was a significant positive correlation between PTX3 expression and the grade of gliomas in the CGGA cohort." (PMID 35855654, 2022). "When it comes to GBM, PTX3 can promote the proliferation and metastasis of glioma cells, which has been found to indicate a terrible prognosis." (PMID 35982954, 2022). "The deletion of 1p36, 9p21, and the amplification of 1p32, 7p11, and 12q13‐15 were more related to glioma with high expression of PTX3." (PMID 35855654, 2022). "IHC staining further showed that PTX3 expression in glioma positively correlated with the malignant degree of gliomas." (PMID 35855654, 2022). "Generally, the immunosuppressive property of PTX3 makes it a potential new therapeutic target and prognostic marker for the treatment of gliomas." (PMID 35855654, 2022). "Therefore, not only that PTX-3 could be useful as a diagnostic tool, but also as a prognosis tool and it could support pathologists as a reliable high accurate predictor of various grades of gliomas and meningiomas, in correlation with genetic profile." (PMID 36499628, 2022). "The Kaplan–Meier curve also proved that the high expression of PTX3 had poor prognostic significance in 14 other cancers in addition to glioma." (PMID 35855654, 2022). "SPOCD1 encodes a protein that pertains to the transcription factor S-II (TFIIS) family of transcription factors and accelerates the proliferation and metastasis of glioma cells by up-regulating PTX3." (PMID 35941292, 2022). "The immunosuppressive property of PTX3 makes it a potential new therapeutic target and prognostic marker for the treatment of gliomas." (PMID 35855654, 2022). "PTX3 was also associated with reduced overall survival (OS) in LGG, pan‐glioma samples in the CGGA dataset." (PMID 35855654, 2022). "In glioma, previous study confirmed that decreased the expression of PTX3 impaired glioma cells proliferation and invasion ability." (PMID 32984316, 2020). "In the TCGA database, high PTX3 expression suggested worse survival outcome than low PTX3 expression in glioma (P < 0.001)." (PMID 32984316, 2020). "Based on treatment outcome after first course, PTX3 expression is significantly increased in patients with PD than other three groups (CR, PR, and SD) in glioma from the TCGA database (P < 0.001)." (PMID 32984316, 2020). "Increased circulating levels of PTX3 were observed in myeloproliferative neoplasms, lung cancers, soft tissue sarcomas, gliomas, pancreatic and hepatocellular carcinomas." (PMID 32345771, 2020). "Increased circulating levels of PTX3 were observed in myeloproliferative neoplasms, soft tissue sarcomas, lung cancers, pancreatic carcinomas, gliomas, and hepatocellular carcinomas." (PMID 31019517, 2019). "PTX3, FAPB7, POSTN, and PDPN are associated with increased glioma invasion, and both PDPN and CHI3L1 reportedly contribute to radio-resistance in glioblastoma." (PMID 29523123, 2018). "In previous clinical studies, PTX3 was found to be increased in other tumors such as liposarcomas, glioma, lung and prostate cancer compared to paired healthy controls or to benign hyperplasia." (PMID 26859579, 2016). "Most other studies have suggested that increased PTX3 expression promotes the severity of tumor malignancy in various types of cancer, including liposarcoma, lung cancer, glioma, and pancreatic carcinoma." (PMID 27458153, 2016). "PTX3 expression also positively correlates with tumor grade and severity in glioma, representing PTX3 as a marker of cancer-related inflammation and malignancy." (PMID 24457902, 2014). "The absence of significant correlation in lower-grade gliomas (G2) and IDH-mutant cases suggests that the prognostic significance of PTX3 is more pronounced in aggressive tumor phenotypes, warranting further investigation into its mechanistic role in glioma pathophysiology." (PMID 40656950, 2025).